INS (insulin)
Diseases named in the same sentence as INS in open-access papers (continued):
Sharing a sentence is not in itself a finding about the gene and the disease.
migraine (continued). "NPY Y1 deficient mice seem to display mild hyperinsulinaemia and obesity, and this could be relevant in the interactions between glucose and insulin metabolism and migraine." (PMID 37569369, 2023). "This connection may explain the strong links between insulin and female sex hormones and the deterioration of migraines due to estroprogestins, and it could support the theory of menstrual migraines." (PMID 35627115, 2022). "Besides its role in migraines, animal studies revealed an association between CGRP and the modulation of insulin and glucagon production." (PMID 35627115, 2022). "A potential pathological link between nutrition and migraine may be a disturbed glucose-insulin metabolism." (PMID 35207390, 2022). "Impaired insulin sensitivity was documented in migraine patients." (PMID 35033025, 2022). "Dysfunction in the insulin signaling pathway may, therefore, explain the reduced metabolism observed in patients with migraine." (PMID 33958992, 2021). "Migraine patients have been reported to have increased insulin levels compared to controls." (PMID 34177788, 2021). "The physiological implications include energy production, the trigger of the inflammatory response through via TLR4 signaling pathway associated with pain pathogenesis, worsening pain, and a link to insulin resistance that is proposed to be a part of migraine pathophysiology." (PMID 34531722, 2021). "In addition to its role in the pathogenesis of migraine, calcitonin gene‐related peptide (CGRP) is implicated in the regulation of insulin secretion." (PMID 33855218, 2021). "A study on male rats observed that insulin and glucagon can alter the transmission of nociceptive inputs in the trigeminal–cervical complex suggesting another important potential neurobiological link between migraine and impaired metabolic homeostasis." (PMID 32481555, 2020). "Therefore, higher levels of insulin in migraine patients help us predict reduced insulin sensitivity." (PMID 32670707, 2020). "Insulin has been found as the most significant related gene in migraine." (PMID 32231773, 2019). "The finding indicates that insulin is the most important gene relative to migraine." (PMID 32231773, 2019). "Knowing their role in migraine pathophysiology, decreasing insulin and glucose levels could explain our results." (PMID 31357685, 2019). "Some prophylactic treatments induce increase of weight, insulin and leptins that can counteract the therapeutic effect; it is the “prophylactic paradox”: a long lasting migraine could be worsened by the drug-induced obesity." (PMID 28132360, 2015). "Although the exact biological mechanisms that connect migraine to AD remain to be fully determined, existing evidence indicates that overlapping pathological processes—such as impaired insulin signaling within the brain and persistent neuroinflammation—may play a shared role." (PMID 41581199, 2026). "However, the precise role neuroinflammation and mitochondrial dysfunction play as contributing factors, in the complex interplay with brain insulin resistance, in both migraine chronification and AD pathologic cascade and clinical progression, is still a question of debate." (PMID 38913047, 2024). "Additionally, insulin signalling alterations may be related to migraine disorders since insulin plays a vital role in synaptic plasticity, neurotransmission, and neuroinflammation in the central nervous system." (PMID 36808568, 2023). "A rodent study also demonstrated supportive evidence for the role of feeding hormones, such as insulin, leptin, and glucagon, on trigeminovascular sensory processing, thus supporting the interaction between sensory, metabolic, and homeostatic systems in migraine." (PMID 37569369, 2023).
migraine (continued). "Intense genetic research has also been performed on glucose-related traits such as fasting glucose, insulin measures, and glycated haemoglobin (HbA1c), used to diagnose, and control T2D, which are also important risk factors for migraine even in the non-diabetic range." (PMID 35627115, 2022). "Also, altered insulin metabolism could be related to leptins and nitric oxide (NO) stress, both inducing inflammatory effects involved in migraine pathogenesis." (PMID 28132360, 2015). "Another study reported that children with migraine showed significantly higher levels of pentraxin-3 (PTX-3), insulin, and insulin resistance, suggesting a role for inflammation and vascular endothelial dysfunction in pediatric migraine." (PMID 40149800, 2025). "Furthermore, these findings align with the emerging literature that implicates insulin in central nervous system function, reinforcing the potential utility of targeted dietary interventions in modulating both metabolic and neurological outcomes in migraine patients." (PMID 40426647, 2025). "Also, a recent review suggested that brain insulin resistance, resulting in a chronic mismatch between the brain’s energy reserve and expenditure, may be an important mechanism in the development of metabolic abnormalities that drive migraine chronification." (PMID 38347465, 2024). "It has been suggested that insulin, glucagon, and leptin may alter the transmission of nociceptive inputs from the trigeminal nerve to higher brain regions, implying that adipokine signaling could influence specific neural networks involved in the development of migraines." (PMID 39452037, 2024). "In addition, several studies have investigated the increased comorbidity of migraine and glycemic traits, focusing on the dysregulation of glucose or dysglycaemia in migraine patients as possible outcome of disturbed metabolism mainly due to impaired glucose-insulin metabolism." (PMID 36808568, 2023). "Investigating the effects of disturbed insulin secretion such as in type-2 diabetes patients on CGRP concentrations and migraine prevalence would provide further evidence of a reciprocal relationship." (PMID 36175833, 2022). "Although antagonism of CGRP signalling has demonstrated significant efficacy in migraine prophylaxis, the effects on insulin function have not yet been assessed in patients." (PMID 36175833, 2022). "In addition to its role in migraine, animal models indicate a link between CGRP and the regulation of insulin and glucagon secretion." (PMID 33855218, 2021). "Insulin sensitivity is clearly impaired in migraine, even in young, non-obese, non-diabetic, normotensive patients." (PMID 33958992, 2021). "The migraine prevalence in patients treated with insulin, oral anti-diabetic agents and no medication were 27.9, 29.5 and 23.1 %, respectively (p-value = 0.549)." (PMID 27617234, 2015). "Given the design of the current study, it is not possible to determine whether improvements in insulin sensitivity and reductions in inflammation contribute to the beneficial effects of cabergoline in migraine patients." (PMID 40168298, 2025). "In this study, insulin sensitivity (ISI-Stumwoll index) and oral glucose insulin sensitivity (OGIS-180 index) were significantly altered in migraine patients when compared with non-migraine patients (0.28 ± 0.12 vs. 0.18 ± 0.09; and 455.4 ± 59 vs. 515.7 ± 088.2, p < 0.01; respectively)." (PMID 34177788, 2021). "Therefore, hypotheses of impaired insulin sensitivity in migraine could not be refuted nor confirmed." (PMID 39083723, 2024).
Polydipsia (50 papers, 2011 to 2025). Excessive thirst manifested by excessive fluid intake. "Lastly, similar to other epidemiological studies we used only clinical criteria to define T1D presence of classic clinical presentation at diagnosis, such as polyuria, weight loss, polydipsia, and the need for continuous insulin use since then." (PMID 40801171, 2025). "At the age of 20, it was decided to introduce insulin therapy, using a basal-bolus scheme after experiencing glycemic decompensation with symptoms of polyuria, polydipsia, and unexplained weight loss during steroid therapy." (PMID 40303645, 2025). "Following the initiation of insulin therapy, symptoms of polyuria, polydipsia, and weight loss are reversed." (PMID 37012937, 2023). "In adult patients with T2DM who are symptomatic (polyuria, polydipsia, weight loss) and present with HbA1c > 9%, insulin-based therapy is recommended to improve blood glucose control." (PMID 32489427, 2020). "The present study found that BZYQF significantly improved the symptoms of polyuria, polyphagia, polydipsia, and weight loss in T2DM rats, reduced the levels of FBG, TC, and TG, and increased insulin levels and HOMA-β in the serum of T2DM rats." (PMID 40573235, 2025). "In the present study, we have demonstrated that RDR can improve diabetic features such as polydipsia, polyphagia, and reduced body weight, lower plasma glucose levels, and raise plasma insulin concentrations in STZ-induced diabetic rats." (PMID 39201631, 2024). "Specifically, AACE indicates that patients with HbA1c >10%, symptomatic with polyuria, polydipsia, or polyphagia, will benefit more from starting insulin." (PMID 38559691, 2024). "In a different experiment involving animals, giving blueberry ACN extract to T2DM mice improved glucose tolerance and blood glucose levels; reduced polydipsia and polyuria symptoms; and reduced TC, TG, and insulin levels." (PMID 37241737, 2023). "His fasting blood glucose was 551 mg/dL with polydipsia and polyuria, and he was immediately started on insulin glargine." (PMID 37535407, 2023). "It should be noted that rats in the INS group showed slight polyphagia, polydipsia 5–7 h after insulin injection, which became worse gradually with the metabolism of insulin." (PMID 34955862, 2021). "SMSO treatment significantly improved the symptoms of weight loss, polydipsia, reduced FBG level, increased plasma insulin levels, reduced plasma lipids levels, and protected islet injury." (PMID 29853958, 2018). "Moreover, among the three groups, the rats in the HFHS+STZ group presented the most obvious clinical symptoms of GDM with polydipsia, polyphagia, and body weight gain, and high IR level and low insulin sensitivity." (PMID 36107823, 2022). "A reduction in nonfasting BGL was associated with improved insulin sensitivity whilst reducing polyphagia and polydipsia." (PMID 35265127, 2022). "Although the results indicated curcumin had an insignificant effect on improving weight loss in diabetic rats, curcumin has a strong synergistic effect that enhances the stability of insulin glycemic control and anti-apoptotic ability, as well as reducing polydipsia and polyuria." (PMID 34955862, 2021). "Polyuria and polydipsia persisted despite euglycemia under insulin treatment." (PMID 34055366, 2021). "Insulin reversed both polyuria and polydipsia in STZ-treated rats." (PMID 27073901, 2016). "However, naringin, ramipril and insulin treatment of the diabetic rats significantly (p<0.05) reduced polydipsia compared to the untreated diabetic rats." (PMID 26967518, 2016). "The n5-STZ model develops the classical diabetic picture of T2DM, where it elevated fructosamine, sharply reduced pancreatic insulin stores with the consequent decrease in basal insulin, besides polyphagia and polydipsia that are aggravated by I/R in adulthood." (PMID 26262991, 2015).
Polydipsia (continued). "In this study, it was also observed that BG and daily water intake of diabetic rats were treated with vanadium or insulin, while the non-treated diabetic rats of CD stayed hyperglycemic with polydipsia during the experiment." (PMID 24842144, 2014). "Although glycemia improved significantly in diabetic rats treated with lycopene + 1 U/day insulin, it is possible that small glycemic variations throughout the day culminate in episodes of glycosuria, which could explain the polyuria observed in DI1U + LYC rats, and consequently polydipsia." (PMID 38892513, 2024).
intrauterine growth restriction (49 papers, 2004 to 2025). "PAECs from intrauterine growth restriction fetuses were less sensitive to INS which caused significantly decreased cell motility, growth, tube formation, and NO production." (PMID 31876736, 2019). "Reduced insulin/insulin-like growth factor signaling (IIS) is a major cause of symmetrical intrauterine growth retardation (IUGR), an impairment in cell proliferation during prenatal development that results in global growth defects and mental retardation." (PMID 27048332, 2016). "Furthermore, reduced adiponectin levels in mothers was associated with intrauterine growth restriction, association that is influenced by the percentage of adipose tissue and insulin resistance." (PMID 34657185, 2022). "For example, animal models have shown that protein restriction during pregnancy (rodent model) is linked to intrauterine growth restriction and reduced offspring insulin signaling, and a high protein intake during pregnancy has been associated with increased offspring body weight and body fat." (PMID 32397092, 2020). "In the pathophysiology of fetal growth restriction, the reduction of insulin and of IGF-1 levels causes a decrease in the proliferation of renal cells, which may affect the pressure of glomelluric capillaries." (PMID 30939608, 2019). "As consistent with previous studies, LPD offspring showed lower fasted insulinemia at weaning, compared to control offspring, which may be caused by aberrant insulin secretion due to intrauterine growth restriction." (PMID 28264458, 2017). "Fetal programming associated with intrauterine growth restriction (IUGR) predisposes offspring to lifelong metabolic dysfunction, including impaired skeletal muscle glucose metabolism and poor insulin secretion." (PMID 40559370, 2025). "Vasculopathy due to hyperglycaemia and increased insulin secretion can lead to intrauterine growth restriction (IUGR) and small for gestational age (SGA)." (PMID 36309618, 2023). "Secondary outcomes for adverse pregnancy outcomes include non-normal gestational weight gain (GWG) (excessive GWG or insufficient GWG), insulin use during pregnancy, cesarean section, premature delivery, macrosomia, and fetal intrauterine growth restriction." (PMID 36078441, 2022). "Information about adverse pregnancy outcomes will be collected from prenatal and delivery records, including excessive GWG or insufficient GWG, insulin use during pregnancy, cesarean section, premature delivery, macrosomia, and fetal growth restriction." (PMID 36078441, 2022). "This study aimed to investigate the effects of leucine with different levels on the insulin resistance in intrauterine growth restriction/retardation (IUGR) piglets." (PMID 31847151, 2019). "In several studies, maternal protein restriction has been shown to program an insulin-resistant phenotype in rodents, especially in consequence of catch-up growth following intrauterine growth restriction." (PMID 28273874, 2017). "Sixty-two infants were enrolled in the study; five infants were excluded because of intrauterine growth restriction, three infants for cerebral lesions and two for an early need for insulin therapy, leaving 52 eligible infants for evaluation." (PMID 27973552, 2016). "Infants affected by intrauterine growth restriction have low concentrations of insulin and IGF-1 at birth, and normalization of these parameters occurs in the postnatal period." (PMID 23476780, 2013). "It has been demonstrated that intrauterine growth restriction can induces apoptosis in fetal kidney and in beta cells of pups compromising the adult renal function and insulin secretion, respectively." (PMID 23675529, 2013). "In response to intrauterine growth restriction induced by placental insufficiency in ewes, fetal liver growth was reduced and gene expression of pathways affecting nutrient sensing, insulin responsiveness and gluconeogenesis were altered." (PMID 20576133, 2010).
intrauterine growth restriction (continued). "These hormonal changes include increasedmaternal insulin levels, as reported in a low-protein animal modelof intrauterine growth restriction." (PMID 17497031, 2007). "Symptoms of this, i.e. a hampered blood glucose clearance after insulin stimulation, which could be facilitated by a disordered lipid metabolism or an intrauterine growth restriction have been found in a feeding trial with Goettingen Minipigs." (PMID 30231878, 2018). "Data showed that LBW and intrauterine growth restriction could affect the insulin and IGF axes around birth." (PMID 25679207, 2015). "However, in the relatively small group of participants who had suffered from intrauterine growth restriction, those with more rapid weight gain from birth to term had higher fasting insulin concentrations." (PMID 26327229, 2015). "Interestingly, the thrifty phenotype hypothesis has been challenged by the “fetal salvage” hypothesis which offers a different explanation for the insulin resistance seen in those affected by intrauterine growth restriction." (PMID 23476780, 2013). "One phenotype exhibits significant placental and fetal growth restriction (PI-FGR), impaired placental nutrient transport, and significant reductions in umbilical insulin and IGF1." (PMID 37374044, 2023). "Paternal ethanol exposure can trigger intrauterine growth retardation (IUGR) in offspring, along with altered insulin signal and disrupted lipid homeostasis in the livers of offspring." (PMID 36499404, 2022). "In clinical cases, primarily reported in pregnancies complicated by intrauterine growth restriction (IUGR), circulating glucose, insulin, IGF-1, and IGF-2 concentrations in the umbilical cord are significantly decreased." (PMID 28786951, 2017). "It is characterized by intrauterine growth retardation (IUGR), less frequent diabetic ketoacidosis, requirement of low initial dose of insulin for treatment, and early remission." (PMID 26839896, 2016). "SGA newborns might have intrauterine growth restriction (IUGR), which can limit β-cell replication and result in lower fetal insulin secretion and poor fat synthesis and deposition." (PMID 35736455, 2022). "Greater fetal growth restriction in intact IUGR fetuses indicates that the adrenal medulla plays a major role in coordinating inhibition of fetal growth and asymmetry of growth as glucose, oxygen, and insulin concentrations are similar among IUGR groups." (PMID 25584967, 2015). "GLUT4 expression was not stimulated by 3 hours of insulin stimulation in the subjects born with intrauterine growth retardation." (PMID 25713812, 2015). "We previously reported that early catch-up growth following fetal growth restriction promoted restoration of fat storage but did not induce excess of fat mass or unfavorable changes either in body composition or in insulin sensitivity at one year of age." (PMID 24979613, 2014). "In humans, a relationship between intrauterine growth restriction (IUGR) and cardiac diseases, hypertension, type 2 diabetes, resistance to insulin, and obesity has been well documented, making evident the role of prenatal programming as a determinant of diseases in the adult." (PMID 22142502, 2011). "Likewise, low birthweight, associated with intrauterine growth restriction (IUGR), has been related to a higher incidence of cardiovascular disease and insulin non-dependent diabetes in adult life." (PMID 34071717, 2021). "However, in the carunculectomy model of fetal growth restriction (FGR), carunculectomised ewes have increased glucose concentration, without any increase in insulin, suggesting that there may be a pregnancy-specific impairment of insulin secretion during sheep pregnancy." (PMID 15352999, 2004).